MNT (MAX network transcriptional repressor)
Description:
Binds DNA as a heterodimer with MAX and represses transcription. Binds to the canonical E box sequence 5'-CACGTG-3' and, with higher affinity, to 5'-CACGCG-3'.
Synonyms: bHLHd3; ROX; MXD6; MAD6; lncRNA-HAL
Tractability: No criterion of Open Targets' tractability assessment is met for any kind of drug.
Gene: Protein-coding gene on chromosome 17 (2,384,073 to 2,401,142, reverse strand). Ensembl gene ENSG00000070444.
Subcellular location: Nucleus
Subcellular location (Human Protein Atlas): Nucleoplasm
Gene Ontology:
Molecular function: DNA-binding transcription repressor activity, RNA polymerase II-specific; identical protein binding; protein binding; RNA polymerase II transcription regulatory region sequence-specific DNA binding; DNA-binding transcription factor activity; DNA-binding transcription factor activity, RNA polymerase II-specific; RNA polymerase II cis-regulatory region sequence-specific DNA binding; chromatin binding; DNA binding; protein dimerization activity
Biological process: negative regulation of transcription by RNA polymerase II; regulation of transcription by RNA polymerase II; transcription by RNA polymerase II
Cellular component: Mad-Max complex; nucleoplasm; nucleus; chromatin; RNA polymerase II transcription repressor complex
Genetic constraint (gnomAD): Loss-of-function variants: 13 observed, 33.4 expected, observed/expected ratio (o/e) 0.39, 90% interval 0.25 to 0.62. The synonymous counts are far from expectation, so gnomAD's model fits this gene poorly and the ratio says little. Missense variants: 715 observed, 679.05 expected, observed/expected ratio (o/e) 1.05, 90% interval 0.99 to 1.12. Synonymous variants: 405 observed, 311.95 expected, observed/expected ratio (o/e) 1.3, 90% interval 1.2 to 1.41.
Homologues: Orthologues: chimpanzee MNT (98% identical), macaque MNT (98% identical), guinea pig MNT (95% identical), rabbit MNT (95% identical), mouse Mnt (94% identical), dog MNT (93% identical), pig MNT (93% identical), rat Mnt (92% identical), tropical clawed frog mnt (61% identical), zebrafish mnta (49% identical), Caenorhabditis elegans mdl-1 (12% identical). Paralogues in human: MXI1 (13% identical), MXD3 (11% identical), MXD1 (11% identical), MXD4 (10% identical).
Diseases named in the same sentence as MNT in open-access papers:
MNT is named in the same sentence as 27 diseases in open-access papers, as found by Europe PMC text mining. Sharing a sentence is not in itself a finding about the gene and the disease. The quoted sentences say what the papers report.
leukemia (4 papers, 2016 to 2021). A malignant (clonal) hematologic disorder, involving hematopoietic stem cells and characterized by the presence of primitive or atypical myeloid or lymphoid cells in the bone marrow and the blood. "Together, these results indicated that MNT knock down inhibited myeloid differentiation, a common phenomenon observed in several leukemia subtypes while its induced expression (such as via ATRA treatment) triggered myeloid differentiation." (PMID 26506232, 2016). "Thus, targeting E6AP or enhancing expression of MNT can have therapeutic implications in rescuing myeloid differentiation in leukemia and other cancers where MNT is a potential transcriptional repressor." (PMID 26506232, 2016). "The following sections summarize the eight top-ranked genes in some of the major drug classes (FLT3, CASP8AP2, L2HGDH, MNT, BAZ2B, MZF1, BEX2, and SMARCA4) that are highly likely to have notable biological significance in leukemia." (PMID 29298978, 2018). "Here we describe that MXD1, but not MYC or MNT, localizes to the nucleolus in a wide array of cell lines derived from different tissues (carcinoma, leukemia) as well as in embryonic stem cells." (PMID 27588501, 2016).
cervical cancer (3 papers, 2015 to 2020). A primary or metastatic malignant neoplasm involving the cervix. "We found that HPV E6/E7-related master regulators (ENO1, FOSB, PA2G4, SOX9, TEAD4, FOXO4, and MNT) were significantly differently expressed (p < 0.001) in the cervical cancer TCGA samples (n = 306) than in normal cervix (n = 11) tissue." (PMID 28670312, 2017). "The following genes ENO1, FOSB, PA2G4, SOX9, and TEAD4 were highly expressed in cervical cancer in comparison to normal cervix (p < 0.001), while FOXO4 and MNT were significantly lower in cervical cancer (p < 0.001)." (PMID 28670312, 2017).
hepatocellular carcinoma (3 papers, 2013 to 2022). A malignant tumor that arises from hepatocytes. "Meanwhile, liver-specific Phb1 knockout (KO) mice develop hepatocellular carcinoma (HCC) spontaneously by regulating MAX, MNT and MATα1." (PMID 36348375, 2022). "To investigate the mechanism underlying the knockdown of miR-210 mediated growth delay in SMMC-7721/Lv-anti-210 xenograft, we analyzed protein expression of HIF-1α, MNT, EFNA3 and AIFM3 genes in human hepatoma xenograft by Western blot." (PMID 23618526, 2013). "The Western blot results indicated that knockdown of miR-210 decreased HIF-1α protein and increased protein expression of MNT, EFNA3 and AIFM3 genes in human hepatoma xenograft." (PMID 23618526, 2013).
myeloid leukemia (3 papers, 2016 to 2025). A clonal proliferation of myeloid cells and their precursors in the bone marrow, peripheral blood, and spleen. "Here, we have established for the first time to our knowledge, the dependency of certain myeloid leukemias on the bHLHLZ transcription factor MNT." (PMID 41140443, 2025). "In order to further substantiate their physical interaction in physiologically relevant myeloid cells, we assessed physical interaction between endogenous E6AP and MNT in myeloid leukemia cell line HL60." (PMID 26506232, 2016). "In this study, for the first time to our knowledge, we show that mouse and human myeloid leukemias provoked by oncogenic mixed lineage leukemia (MLL) fusion proteins are dependent on the MYC family member MNT (MAX network transcriptional repressor), which is highly expressed in these AMLs." (PMID 41140443, 2025).
Lissencephaly (2 papers, 2017). A spectrum of malformations of cortical development caused by insufficient neuronal migration that subsumes the terms agyria, pachygyria and subcortical band heterotopia. "Deletions involving several of the highly differentiated genes in this region have been suggested to contribute to MDS, including PAFAH1B1 (the primary lissencephaly-related gene, also known as LIS1, CFA9:46,647,994–46,727,422), MNT (CFA9:46,466,709–46,482,614) and SMG6 (CFA9:46,161,531–46,405,748)." (PMID 28806925, 2017). "At about the same time, the MNT gene (previously referred to as ROX) was identified during chromosomal mapping studies looking for genes that might contribute to Miller-Dieker lissencephaly, a congenital malformation disorder characterized primarily by lissencephaly (smooth brain)." (PMID 28230739, 2017).
lymphoma (2 papers, 2022 to 2023). A malignant (clonal) proliferation of B- lymphocytes or T- lymphocytes which involves the lymph nodes, bone marrow and/or extranodal sites.
malignant melanoma (2 papers, 2010 to 2021). "Our results showed that transcript expression levels of c-RET and GDNF in MNT-1 and HM3KO human malignant melanoma were definitely higher than those in NHEM cells, while GFRa1 expression levels were comparable in these cells." (PMID 20422010, 2010).
neuroblastoma (2 papers, 2016 to 2021). Neuroblastoma (NB) is the most common solid, extracranial childhood tumor. "In fact, a previous report showing MNT overexpression in neuroblastoma cells retained differentiation potential also augments and supports our findings that MNT has a pivotal role in differentiation per se." (PMID 26506232, 2016).
mammary adenocarcinoma (1 paper, 2023). "As a MYC antagonist, MNT was originally considered a tumour suppressor and this was supported by an early study showing that mice with mammary-specific Mnt deletion developed mammary adenocarcinoma." (PMID 36755068, 2023).
pancreatic cancer (1 paper, 2023). "Its impact on downstream target genes like E2F3, EFNA3, GIT2, MNT, ZNF462, HOXA9, and EGR3 underscores its significance in shaping the aggressive phenotype of pancreatic cancer cells." (PMID 38132457, 2023).
cancer (10 papers, 2013 to 2024). A tumor composed of atypical neoplastic, often pleomorphic cells that invade other tissues. "This is mostly driven by the cancer-related TF MAX whose binding is antagonized by many other bHLH TFs such as MNT, MXD1, and MXD4." (PMID 39013578, 2024). "The indispensable genes are directly associated with cancers, especially EGFR, MAX, MNT, SMAD3." (PMID 33968733, 2021). "Thus, the MYC/MAX/MNT system that drives cell growth and proliferation is robustly set to an off state during normal homeostasis, whereas in cancer, the system is locked to a pathological on state." (PMID 28583252, 2017). "To determine whether mNT and NAF-1 function in the same, or different pathways to mediate these functions in cancer cells we generated double shRNA cell lines with suppressed expression of both mNT and NAF-1." (PMID 28426722, 2017). "Overexpression of mNT also protects cells from oxidative stress and ferroptosis, whereas overexpression of NAF-1 protects cancer cells from oxidative stress and apoptosis." (PMID 28426722, 2017). "Suppression of mNT or NAF-1 protein expression also results in the over-accumulation of iron and ROS in the mitochondria of cancer cells and the activation of autophagy and apoptosis." (PMID 28426722, 2017). "miR-210, miR-17-92, miR-31, miR-221 and miR-222 have been documented to be down-regulated in radioresistant cancer cells, to regulate the expression of AIFM3, MNT and PTEN respectively, and to promote cancer radioresistance." (PMID 24283459, 2013).
tumor (7 papers, 2017 to 2023). "This antagonism can explain why the deletion of MNT leads to tumor formation in mouse mammary epithelium and T-cells." (PMID 33419981, 2021). "Nonetheless, the apparent targeting of MNT by hypoxia and miR-210 during cholangiocarcinogenesis and in GSCs reinforces the notion that MNT functions as a tumor suppressor." (PMID 28230739, 2017). "However, in most studies, MNT acted as a tumor suppressor and was a functional antagonist of MYC by repressing its activities related to cell cycle, proliferation, and apoptosis." (PMID 33261009, 2020). "Beyond cell culture models, both experimental mouse models and interrogation of the MNT locus in human tumors provide supporting evidence that MNT may be a bonafide tumor suppressor." (PMID 28230739, 2017). "MNT was first described as a MYC antagonist and tumor suppressor." (PMID 34572909, 2021).
infection (2 papers, 2019 to 2023). The state of being infected such as from the introduction of a foreign agent such as serum, vaccine, antigenic substance or organism. "In recent studies on the infection mechanism of Candida yeasts to the host, mutant strains lacking the PMT or MNT gene family encoding the protein O‐mannosyltransferase or α‐1,2‐mannosyltransferase, respectively, involved in the biosynthesis of O‐linked sugar chains are frequently used." (PMID 30652080, 2019).
MNT also shares sentences with these, for which no sentence is quoted: breast carcinoma (2 papers); atherosclerosis (1); Burkitt lymphoma (1); chronic myeloid leukemia (1); colon cancer (1); glioma (1); lung carcinoma (1); myeloid neoplasm (1); Obesity (1); pheochromocytoma (1); prostate carcinoma (1); renal carcinoma (1); renal clear cell carcinoma (1); schizophrenia (1).